TNF (tumor necrosis factor)
Diseases named in the same sentence as TNF in open-access papers (continued):
Sharing a sentence is not in itself a finding about the gene and the disease.
heart failure (continued). "At least some of RA patients with heart failure may benefit from anti-TNF treatment, as it results not only in the reduction of inflammation but also contributes significantly to the improvement of cardiac function." (PMID 29895751, 2018). "Also, five of these six patients were anti-TNF unresponsive as our cases (Only one patient used rituximab as a first line biologic agent because of advanced heart failure)." (PMID 30400666, 2018). "This potentially beneficial response of resident cardiac stem cells to TNF may have contributed to the adverse effects of anti-TNF therapies in human heart failure." (PMID 28955710, 2017). "Although the direct effects of cytokines on ion transports in the kidney were no studied yet, the observation that heart failure is associated with enhanced renal TNF-α and IL-6 expression along tubular cell apoptosis supports such a role." (PMID 28674538, 2017). "Notably, increased level of TNF-α is found in patients with heart failure, and TNF-α has been proven to serve as a prognostic factor of heart failure." (PMID 28513772, 2017). "Moreover, overexpression of TNF-α in transgenic mice led to myocarditis, production of nitric oxide, and heart failure." (PMID 29267325, 2017). "Specifically, studies indicate that TNFR2 effectively protects against TNFα-mediated heart failure." (PMID 29258611, 2017). "Because of the moderate activity of small molecules, we can deduce that these molecules may prevent apoptosis, left ventricular dysfunction, left ventricular remodeling and so on to cure heart failure through targeting TNF-α." (PMID 27095146, 2016). "If TNF-α is a detrimental factor or mediator for myocardial failure, inhibition of TNF-α either in blood or in TNF-α receptors may be an effective treatment for heart failure." (PMID 27095146, 2016). "Early studies demonstrated that TNF-α may be one of several potentially important maladaptive mechanisms involved in a maladaptive response leading to heart failure." (PMID 27929425, 2016). "TNF-α may play a role on the high levels apoptosis and in the low proliferative response observed in patients with heart failure." (PMID 27138039, 2016). "The inflammatory response expressed by PTX3 had a significant relationship with age, heart failure, infarct size, impaired flow in the infarct-related artery, and renal function and positively correlated with neopterin, TNF-α, 8-hydroxy-2′-deoxyguanosine, and nitrite/nitrate." (PMID 25922551, 2015). "TNF-α levels increase in patients with advanced heart failure and correlate with prognosis." (PMID 26029107, 2015). "It appears that TLR4 is particularly important for continuous monocyte activation in heart dysfunction, and that TLR4 overexpression is accompanied by secretion of proinflammatory cytokines such as CRP and TNF-α, as well as a known biomarker of cardiac failure—pro BNP." (PMID 26030867, 2015). "In this regard, TNF-α production is enhanced in the heart of spontaneously hypertensive rats and in the failing human heart; this then contributes to cardiac remodeling and malfunction, thereby speeding up heart failure progression." (PMID 26112171, 2015). "PTX ameliorates LVEF in patients with noninfectious heart failure in association with downmodulation of inflammatory biomarkers, such as TNF." (PMID 25789471, 2015). "Increasing evidence indicates that inflammatory cytokines, including TNF-α, interleukin 1β (IL-1β), and IL-6, are elevated in, and may contribute to, heart failure." (PMID 26029107, 2015). "Similar behaviour has been reported with other cytokines such as TNF-α in heart failure." (PMID 25922663, 2015). "High levels of IL-6 and TNF-α predicted incident heart failure." (PMID 25722960, 2015). "The correlations between neopterin concentration and TNF-α or INF-γ in heart failure were found." (PMID 25214716, 2014).
heart failure (continued). "The cardiac levels of immnoreactive IL-1 and TNF-α in the same animals were elevated at 6, 24, and 48 h after renal ischemia, and echocardiography revealed left ventricular dysfunction, a likely sign of heart failure, at 48 h after renal IRI." (PMID 26266925, 2014). "Interestingly, ADAMTS4 synthesis in macrophages increases in response to tumor necrosis factor (TNF)-α and interleukin (IL)-1β, cytokines which are found increased in the myocardium of heart failure patients, suggesting a role in heart failure development." (PMID 24595230, 2014). "Increased TNF-α in autonomic regulatory regions of the brain alters the production of superoxide and nitric oxide, contributing to fluid imbalance and sympathoexcitation in heart failure." (PMID 25984330, 2014). "On the other side, TNF-α is a strong mediator in the progression of heart failure." (PMID 23530831, 2013). "Therefore it was concluded that over-expression of TNF-α and subsequent loss of β-adrenergic responsiveness contributes to the decrease in HRV observed in heart failure." (PMID 22920474, 2013). "The best studied pro-inflammatory cytokine in the scenario of heart failure is TNF-α." (PMID 23740214, 2013). "TNF-α is an important factor in the development and progression of heart failure." (PMID 24086665, 2013). "TNF-α may also contribute to the development of heart failure through apoptosis and the induction of NOS2, producing nitric oxide which exerts strong negative inotropic effects." (PMID 22811738, 2012). "Moreover, large numbers of TNF-α-producing cells and high levels of STAT4 mRNA were associated with the occurrence of heart failure." (PMID 22811738, 2012). "In the present study, TPT treatment may decrease plasma TNF-α, and IL-6 levels, indicating that TPT delay heart failure by inhibiting TNF-α, and IL-6 secretion, and improving immunity system, and strengthen myocardial contractility." (PMID 22569420, 2012). "Elevated levels of biomarkers of systemic inflammation, immune function, and ventricular remodeling, such as C-reactive protein (CRP), tumor necrosis factor (TNF), and endothelin-1, also have been associated with morbidity and mortality among heart failure patients." (PMID 22588803, 2012). "Since many humoral factors such as AngII and TNFα are upregulated in heart failure and increased activin A expression by activating NFκB, the molecules that modulate NFκB activation might be also therapeutic targets to restore GH levels." (PMID 22216087, 2011). "Accordingly, TNF variants selectively activating TNFR2 could be a useful therapeutic regimen in a variety of diseases, including heart failure, autoimmune and neurodegenerative diseases." (PMID 22110694, 2011). "Sustained long-term over-expression of TNF-α provokes the induction of cardiomyocyte apoptosis, which contributes to the pathophysiology of several heart diseases, including dilated cardiomyopathy, myocardial infarction, and heart failure." (PMID 21949832, 2011). "Furthermore, IL-6 and TNF-α have been shown to be independent predictors of mortality in heart failure." (PMID 19909503, 2009). "The effects of TNF-α or LPS on EECs as observed in our study may be of significance in pathological conditions such as cardiac failure and during post inflammatory wound healing where different cytokines are up – regulated in the tissues." (PMID 19272191, 2009). "In heart failure, both the heart itself and activated monocytes are able to secrete TNFα." (PMID 20224758, 2009). "TNF-α antagonism has been shown to adversely affect the clinical status in heart failure but the mechanism remains unknown." (PMID 19946518, 2009). "In this regard, the genetic background may promote the deleterious effects of TNF-α in heart failure." (PMID 18997986, 2008). "In addition, the activation of p38 via MKK6bE may mediate the inflammatory induction of TNF-α and IL-6 in cardiomyocytes and contribute to the development of fibrosis, adverse cardiac remodeling, and heart failure." (PMID 40610735, 2025).
heart failure (continued). "As an example, anti-TNF therapy may even adversely affect incidence of heart failure and death." (PMID 40181186, 2025). "TNF-α stimulates clonal expansion with myeloid skewing, at least in vitro, and increased TNF-α levels were noted in the circulating monocytes of patients with heart failure (including those with aortic stenosis) and DNTM3A mutations as well as in pressure-overload mice models with Jak2 mutations." (PMID 40076674, 2025). "While IL-12p40, IL-15, and TNFα of HF participants with NT-proBNP ≥500 pg/mL were significantly higher than HF participants with NT-proBNP levels of <500 pg/mL, these cytokines do not significantly correlate with NT-proBNP levels, an indicator of heart failure progression." (PMID 41200931, 2025). "Therefore, reducing levels of CRP, TNF-α, and IL-6 in heart failure patients may help to reduce heart failure symptoms and improve the overall health of heart failure patients." (PMID 41179565, 2025). "Studies have shown that patients with decompensated heart failure (HF) have higher LPS concentrations compared to those with stable HF, and the progression of HF is associated with an increase in inflammatory markers such as soluble (s) CD14, tumor necrosis factor (TNF)α, and interleukin 6 (IL-6)." (PMID 40766948, 2025). "In addition, the increase in circulating pro-inflammatory cytokines in heart failure patients, notably, TNF, may also reduce the synthesis of NO by downregulating the expression of endothelial nitric oxide synthase, the key enzyme involved in NO production." (PMID 38396488, 2024). "Analyzed biochemical variables will include heart failure biomarkers, such as NT-proB-type natriuretic peptide (NTproBNP), troponin (hs-TnI), and inflammation markers, such as polymerase chain reaction (PCR), tumor necrosis factor-alpha (TNF-alpha), and interleukin 6 (IL-6)." (PMID 36923954, 2023). "This view is further supported by studies in which reducing the synthesis of TNF-α by decreasing the function of TNF-α-converting enzyme resulted in improved systemic haemodynamic variables while increased levels of the enzyme resulted in worse symptoms of heart failure in rats." (PMID 35309046, 2022). "The presence of pro-inflammatory cytokines, such as TNF-α, IL-1, and IL-6, that may contribute to the pathogenesis of cardiac remodeling, and to systolic and diastolic dysfunction, is frequently described in human heart failure." (PMID 35878343, 2022). "Three clinical trials (ATTACH, RECOVER, and RENAISSANCE) have been performed to test whether TNF inhibitors prevented heart failure (HF) aggravation; these trials were conducted with the hypothesis that TNF-α is a pathologic cytokine contributing to HF progression." (PMID 36430392, 2022). "Moreover, targeting inflammatory cytokines and chemokines, such as IL-1, IL-6, CCL2, TGF-β, TNF-α, could be helpful in heart failure treatment." (PMID 34387811, 2022). "For instance, anti-TNF therapy is often linked with lower risk of cardiovascular events among patients with autoimmune conditions like rheumatoid disease, but shows no or even adverse effects for heart failure or myocardial infarction at high doses." (PMID 35074627, 2022). "Therefore, we propose to consider sTNF receptors rather than TNF-α as a biomarker of inflammation associated with heart failure." (PMID 36428528, 2022). "As secondary inflammatory processes and cytokine secretion may also affect desmin structure and localization at intercalated disks, as shown upon TNF-α-induced caspase cleavage of desmin in heart failure models, anti-inflammatory treatments could be also suggested in desminopathy." (PMID 33923914, 2021). "Thus, it is plausible that TNF inhibition by pyridostigmine may trigger a positive remodeling and decrease heart failure in infarcted SHRs." (PMID 33953291, 2021). "A study reported that anti-TNF treatment does not increase the risk of heart failure." (PMID 35187113, 2021).
heart failure (continued). "On the other hand, aspirin could reduce TNF-α and IL-6 levels in patients with heart failure." (PMID 33969115, 2021). "Interestingly, a similar action of HDACs has been reported in HL-1 cells derived from mouse atrial cardiac muscle, where HDAC inhibition with a class I HDAC-specific inhibitor, MPT0E014, improves mitochondrial OCR following TNF-alpha treatment to model heart failure." (PMID 33802405, 2021). "Similarly, the role of TNF in heart failure remains equivocal." (PMID 32805626, 2020). "Many molecules like troponins, brain natriuretic protein (BNP), ST2/IL-33, C-reactive protein (CRP), TNF, IL-1β, and IL-18 cytokines have been already examined as molecular markers for diagnosing or predicting different cardiac disturbances like myocardial infarction, heart failure, or myocarditis." (PMID 33172097, 2020). "Thus, experimental data from transgenic mouse models might explain the failure of clinical application of anti-TNF-α inhibitors in heart failure patients." (PMID 33053859, 2020). "Also, whether MC-derived TNF-α represents a viable treatment target is questionable given the failure of targeting TNF-α in heart failure patients." (PMID 29329223, 2018). "Elevation of TNF may therefore explain the cardiotoxic effect of anti-TNF agents, however it is not clear whether this cardiotoxicity is clinically relevant to all conditions where increment of TNF is observed or is restricted only to patients with heart failure." (PMID 29895751, 2018). "Therefore, the clearance of TNF-α might be a potential therapeutic strategy to improve cardiomyocyte hypertrophy and heart failure." (PMID 28513772, 2017). "In vitro research has suggested that TNF-α could induce down-regulation of sarcomeric proteins, apoptosis and depression of contractility in cardiomyocytes, indicating that it might play a key role in cardiomyocyte hypertrophy and heart failure." (PMID 28513772, 2017). "In addition, references have demonstrated that SND can cure heart failure by regulation of blood circulation, response to oxidative stress, apoptotic process, inflammatory response, TNF signaling pathway, Hypertrophic cardiomyopathy, PI3K-Akt signaling pathway and Dilated cardiomyopathy." (PMID 27095146, 2016). "However, clinical trials of TNF-α antagonists for curing heart failure failed." (PMID 27095146, 2016). "However, the prolonged activation of NF-κB appears to be detrimental and promotes heart failure by eliciting signals that trigger chronic inflammation through the enhanced elaboration of cytokines, including tumor necrosis factor, interleukin-1, and interleukin-6, leading to cell death." (PMID 26467087, 2015). "Given the link between plaque inflammation and plaque rupture, it is plausible that there might be an early reduction in MI incidence following anti-TNFα treatment, while potential effects on heart failure, if any, may only be noticeable over a longer time period." (PMID 17763428, 2007). "TNF-α, an inflammatory mediator, promotes cardiac fibrosis by activating the NLRP3 inflammasome, providing a potential new target for heart failure." (PMID 40552149, 2025). "The anti-TNF-α treatment has demonstrated high efficacy in inflammatory diseases such as Crohn’s and ankylosing spondylitis, yet understanding the failures and therapeutic insights from treatment protocols regarding it may help to create new directions in heart failure therapy." (PMID 40710370, 2025). "Dapagliflozin increased serum GSH-Px and SOD levels and decreased IL-1β, IL-6, TNF-α and MDA levels (P < 0.05) in a rabbit model of heart failure." (PMID 39874368, 2025). "Multiple randomized clinical trials and observational studies have shown that an omega-3 supplementation significantly reduces inflammatory biomarkers such as C-reactive protein (CRP), IL-6, and TNF-α in patients with CKD and heart failure." (PMID 40806569, 2025).
heart failure (continued). "RIV can also reduce the expression levels of PAR-1, PAR-2, TNF-α, and TGF-β, thereby preventing cardiac insufficiency in a mouse model of myocardial infarction and attenuating cardiac remodeling." (PMID 40755506, 2025). "Calycosin, administered at a dosage of 4.67 mg/kg, effectively reduces the levels of TNF-α and IL-1 in the serum of rats with heart failure induced by ligation of the left anterior descending artery, indicating that calycosin could alleviate the inflammatory response in rats with heart failure." (PMID 39210410, 2024). "Interleukin-6 (IL-6), tumor necrosis factor-α (TNF-α), and CRP have been reported as serum inflammatory markers for heart failure." (PMID 39026227, 2024). "In this context, serum levels of cytokines, including interleukin (IL)-1β and tumor necrosis factor-alpha (TNF-α), and IL-6 are elevated in HD patients, suggesting an adverse role of these substances in the pathogenesis of cardiac failure in these patients." (PMID 39070454, 2024). "Pathways were enriched in the AGE-RAGE signaling pathway in diabetic complications, the TNF signaling pathway, the Rap1 signaling pathway and the MAPK signaling pathway, which was consistent with previous studies in T2DM patients with heart failure." (PMID 36891270, 2023). "Elevated levels of TNF⍺, IL-6, CRP, Galectin-3, IL-2, IL-1β, IL-8, IL-33, and pentraxin-3 are all found in patients with heart failure." (PMID 36816471, 2023). "LPS is one of the strongest proinflammatory mediators and it induces the release of TNF-α, IL-1, and IL6 in the serum of patients with heart failure." (PMID 36771313, 2023). "Various investigators have demonstrated that inflammatory mediators such as TNF-α play a role in the pathophysiology of chronic heart failure, and the role of TNF-α in the pathogenesis of heart failure is widely accepted." (PMID 36428528, 2022). "Its function can be regulated by cytokines, such as IFNγ and TNFα, and it has been proposed, together with CXCL9 and CXCL11, as a biomarker for heart failure and left ventricular dysfunction." (PMID 36364913, 2022). "TNF α is a cytokine, which is rapidly secreted in the myocardium during acute myocardial ischemia in the setting of ACS and in the development of heart failure." (PMID 35683362, 2022). "TNF-α, MMP-2, and MMP-9 act on inflammatory processes, are upregulated during heart failure (HF), and influence ventricular remodeling." (PMID 33441969, 2021). "Overexpression and chronic activation of ADAM17 can trigger excessive release of TNFα, sIL-6R, and CXCR2 on the surface of proinflammatory cells, which play crucial roles in the pathogeneses of several inflammatory diseases, including heart failure." (PMID 34966735, 2021). "SMYAD reduced the expression of heart failure markers and fibrosis markers (collagen I, MMP9, and TNFα) in the heart tissue of model animals after myocardial infarction." (PMID 34367308, 2021). "The role of inflammation in heart failure has been proposed as levels of inflammatory cytokines including tumor necrosis factor (TNF), interleukin (IL)-1β and IL-6 were found to be elevated in heart failure." (PMID 33344515, 2020). "In particular, circulating levels of tumor necrosis factor-α (TNF-α), interleukin-6 (IL-6), IL-2, and IL-1β are known to correlate with disease severity in heart failure patients." (PMID 33321955, 2020). "Pro‐inflammatory cytokines such as TNF‐α, and IFN‐γ promote structural and functional changes in the heart with consequent worsening of heart failure." (PMID 32468694, 2020). "Heart failure evokes inflammation, and TNF-α, IL-6, IL-18, and atrial natriuretic peptide (ANP) can be induced in pressure overload-induced heart failure." (PMID 33597865, 2020). "Tumor necrosis factor α (TNF-α) and the apoptotic signaling molecule BCL2 play important roles in the progression of heart failure." (PMID 33273955, 2020). "Typhaneoside regulates IL-6 and TNF-α as well as MMP-2 and MMP-9 in rats with heart failure after myocardial infarction." (PMID 31201434, 2020).